LEPR (leptin receptor)
Diseases named in the same sentence as LEPR in open-access papers (continued):
Sharing a sentence is not in itself a finding about the gene and the disease.
Obesity (continued). "Arguably an even more important finding was that of the Lep gene and its product leptin, from the Greek for 'thin', The recessive gene mutation (Lepob -- ob for obesity) had been linked to obesity and type 2 diabetes since the early 1950s, as was the mutant db of the leptin receptor gene (Leprdb)." (PMID 21276254, 2011). "Moreover, human LEPR signaling mutations also caused obesity as well as impairments of pubertal development and growth hormone secretion." (PMID 20624279, 2010). "Leptin- or leptin-receptor-deficient mice exhibit severe obesity and diabetes." (PMID 21113299, 2010). "The leptin receptor (LEPR) has been implicated in obesity and diabetes." (PMID 20624279, 2010). "We hypothesized that we would detect rare loss-of-function genetic variants similar to the link between obesity and rare variants in the leptin, leptin receptor and MC4R genes." (PMID 20016785, 2009). "This phenotype may be surprising, given that disruption of leptin receptor expression specifically in AgRP neurons results in mild obesity, suggesting that loss of leptin action via PI3K signaling might result in a similar phenotype." (PMID 19883613, 2009). "We tested the hypothesis that rare loss-of-function ATXN2 variants cause obesity analogous to rare mutations in the leptin, leptin receptor and MC4R genes." (PMID 20016785, 2009). "Previously, exonic polymorphisms in LEPR have been associated with hypertension in obesity." (PMID 19562039, 2009). "It is elsewhere accepted that radiation at a young age may affect the hypothalamus causing leptin receptor insensitivity and, therefore, a polymorphism in the leptin receptor (LEPR) gene, Gln223Arg, might influence susceptibility to obesity in survivors of childhood ALL." (PMID 41228239, 2025). "Lastly, in vivo data using leptin receptor-deficient (db/db) mice, a model of obesity and type 2 diabetes, indicated that TOTUM-63 might prevent the increase in fasting glycemia and glycated hemoglobin (HbA1c) levels over time, compared with the untreated group." (PMID 36835060, 2023). "Although at first sight this effect might be partly explained by the association of leptin with obesity, the leptin receptor is widely expressed in many tissues, including the lung, and thus a direct effect of leptin on pulmonary structures cannot be discarded." (PMID 38086735, 2023). "In obesity, despite increased leptin concentrations, the efficacy of the anorexic effect of this adipokine is decreased and leptin resistance is developed due to a defect in intracellular signaling associated with the leptin receptor or decreases in leptin transport across the blood–brain barrier." (PMID 35745249, 2022). "We tested this hypothesis by examining the antiobesity effect of SFN on two established genetic models of obesity, namely, the leptin-deficient Lepob/ob and the leptin receptor mutant Leprdb/db mice, both of which develop early-onset hyperphagic obesity due to deficient leptin signaling." (PMID 35323110, 2022). "Therefore, understanding leptin and leptin receptor signaling pathways in the pathogenesis of endometriosis will provide new insights for better understanding the association between obesity and endometriosis and also for developing new strategies for treatment." (PMID 36140261, 2022). "The motivation of this study was to determine whether dapagliflozin could improve NASH db/db mice, which are leptin receptor deficient and have obesity, hyperglycemia, hyperinsulinemia, insulin resistance, and fatty liver, widely used as an animal model of NAFLD." (PMID 36059948, 2022). "Similarly, the presence of certain SNPs within LEPR, especially in the gene region coding regulatory and receptor-activation domains (e.g., rs8179183 and rs8179183), has been associated with both overweight and severe obesity." (PMID 34208585, 2021). "Moreover, mutations in the human LEPR cause obesity and pituitary dysfunction." (PMID 34390703, 2021).
Obesity (continued). "Consequently, SARS-CoV-2 MA can be applied to the existing mouse models to better understand the impact of COVID-19 on obesity, such as genetically obese mouse models, including leptin-deficient (ob/ob) and leptin-receptor-deficient (db/db), as well as high-fat diet-induced-obese (DIO) mouse model." (PMID 34204163, 2021). "Furthermore, new techniques, such as mass spectrometry, might reveal new available markers, as in the case of LEPR mutations, useful for early recognition of obesity risk and intervention." (PMID 33261141, 2020). "Our findings indicate that the effects of the LEPR polymorphism on obesity is accentuated in higher BMI groups and that factors which are potentially protective against obesity (i.e. physical activity, diet) may attenuate the obesogenic effects of the gene variant." (PMID 31948470, 2020). "Thus, IOE administration ameliorates leptin receptor deficiency-induced obesity in db/db mice." (PMID 31323977, 2019). "However, in medaka fish, leptin receptor deficiency leads to obesity." (PMID 30551684, 2018). "LEPR 223, 1019, 492, and 976 gene polymorphisms can modulate the nutritional status in normal and also in obese children, fact that should be interpreted in the context of the multiple factors that modulate obesity such as environmental, nutritional, or social factors." (PMID 27015185, 2016). "Thus, obesity associated with acute LepR deficiency induced massive, rapid beta cell expansion." (PMID 27003683, 2016). "There are few studies that associate obesity status with LEP G-2548A and LEPR Gln223Arg polymorphisms, and, even more important, these associations are shown in a racial dependent fashion; that is why it is necessary to determine their influence on obesity in Mexican population groups." (PMID 26064921, 2015). "Thus, insulin-independent diabetes associated with obesity, which have perturbed leptin receptor and/or MC4R signaling, may be resistant to the DPP-4 inhibitor." (PMID 24804243, 2014). "Two other leptin-related animal models of obesity exist: db/db mice which lack Ob-Rb but have functional other receptor subtypes, and obese Zucker fa/fa rats bearing mutation within the extracellular domain of the leptin receptor which reduces the affinity for leptin of all receptor isoforms." (PMID 21286276, 2010). "In the developed countries with a much higher percentage of postmenopausal breast cancer and a higher proportion of obese women, LEPR Gln223Arg polymorphism may be expected to have more impact on risk of the disease compared to the Nigerian population with a lower prevalence of obesity." (PMID 19017403, 2008). "Mutations associated with monogenic obesity follow autosomal recessive (LEP, LEPR, POMC, and PCSK1) or autosomal dominant (MC4R, SH2B1, SIM1, GNAS) modes of inheritance." (PMID 41751424, 2026). "Accordingly, targeted pharmacological therapies, such as metreleptin for patients carrying biallelic LEP variants and setmelanotide for patients with biallelic LEPR, POMC, and PCSK1 variants, are available for selected monogenic obesity forms." (PMID 41489710, 2026). "A preponderance of the LEPR gene polymorphisms is associated with T2DM, obesity, and metabolic syndrome in different populations." (PMID 40551902, 2025). "Monogenic obesity is caused by mutations predominantly in the leptin-melanocortin system, such as LEP, LEPR, POMC, and MC4R genes." (PMID 40636093, 2025). "Genes implicated in monogenic obesity include POMC, LEP, LEPR, MC3R, and MC4R, while polygenic obesity involves variants in genes such as FTO, UCP1-3, MC4R, ADRB1-3, and SLC6A14." (PMID 41302083, 2025). "Any disruption in ligands or receptors involved in melanocortin signaling, such as rare, pathogenic mutations in LEP, LEPR, or MC4R encoding melanocortin 4 receptor, lead to early-onset severe obesity." (PMID 39237720, 2025).
Obesity (continued). "Both human and mouse platelets express the leptin receptor (LEPR, Lepr), and leptin promotes ADP‐induced platelet aggregation, and leptin‐deficient mice show a reduced thrombotic response, linking obesity to thrombosis." (PMID 39375979, 2025). "Collectively, these data demonstrate that chronic activation of Arc non-LepR neurons results in massive obesity." (PMID 40540394, 2025). "In a Turkish study involving 105 children with early-onset obesity and analysis of 41 genes, approximately 10.5% of the variants were found in the SIM1, POMC, PCSK1, MC4R, and LEPR genes." (PMID 40149731, 2025). "It is indicated for patients aged ≥2 years with obesity due to proopiomelanocortin (POMC), PCSK1, leptin receptor (LEPR) deficiencies, or Bardet-Biedl syndrome (BBS), with dosing adjusted by age and weight." (PMID 41393538, 2025). "Specific mutations in genes that participate in the leptin-melanocortin pathway, such as those encoding leptin, leptin receptor (LepR), melanocortin-4 receptor (MC4R), and pro-opiomelanocortin (POMC), are recognized to cause monogenic forms of obesity." (PMID 41321496, 2025). "An example of these mutations is an alteration in leptin structure or leptin receptor (LEPR), leading to the inability of leptin to bind to its specific receptor and contributing to obesity via complex mechanisms that remain not fully understood." (PMID 40297673, 2025). "Recessive forms of severe obesity were identified, caused by homozygous or compound heterozygous mutations in the following genes: LEP (leptin), LEPR (leptin receptor), BBS1 and BBS10 (Bardet–Biedl syndrome), and POMC (pro-opiomelanocortin)." (PMID 40149731, 2025). "The most prevalent genes linked to monogenic obesity are leptin (LEP), leptin receptor (LEPR), and melanocortin 4 receptor (MC4R) genes." (PMID 40024983, 2025). "Setmelanotide (Imcivree®) was approved in 2020 for obesity due to proopiomelanocortin (POMC), leptin receptor (LEPR), or PCSK1 deficiency, and later for Bardet–Biedl syndrome." (PMID 40843857, 2025). "Monogenic forms of obesity are estimated to account for 4% to 6% of severe obesity before age 6, with LEPR and MC4R genes being the most common etiologies.An estimated 5% to 6% of children and adults with obesity have a MC4R germline pathogenic." (PMID 40585884, 2025). "Sustained hyperleptinemia in obesity appears to downregulate LepR expression, likely through receptor saturation and feedback inhibition." (PMID 41516046, 2025). "The highest prevalence of monogenic obesity was observed in a Pakistani population, where 30% of children with obesity carried pathogenic variants in the LEP, LEPR, and MC4R genes." (PMID 40149731, 2025). "Leptin (LEP), produced by adipocytes, regulates obesity in animals by interacting with LEPR in hypothalamic neurons." (PMID 40735833, 2025). "In this context, a recent investigation highlighted the racial differences in the methylation patterns of the nuclear respiratory factor 1 (NRF1), fat mass and obesity-associated (FTO), and leptin receptor (LEPR) genes among children with obesity." (PMID 40427561, 2025). "In contrast, monogenic obesity, caused by a single, rare mutation in genes like LEP, LEPR, POMC, or MC4R, accounts for less than 1% of obesity cases." (PMID 40564803, 2025). "Key genes implicated in monogenic obesity include those involved in the leptin-melanocortin signaling pathway, such as MC4R, LEPR, PCSK1, and POMC, among others." (PMID 40281302, 2025). "Deletion of the leptin receptor (lepR) in PrRP neurons diminishes leptin’s thermogenic effects and promotes obesity, indicating a significant role for these neurons." (PMID 40130157, 2025). "Conversely, leptin blockade or LepR antagonism in obesity or autoimmunity can rebalance the activity of effector/regulatory T cells, reduce pathogenic cytokine production, and enhance immune regulation." (PMID 41516046, 2025).
Obesity (continued). "Clinical advancements include setmelanotide (IMCIVREETM, Rhythm Pharmaceuticals), an MC4R agonist approved for monogenic obesity disorders (POMC, LepR deficiencies)." (PMID 40278960, 2025). "Transgenic db/db mice, which lack the leptin receptor, are highly prone to obesity, becoming obese as early as five weeks of age and reaching peak weight between 10 and 16 weeks." (PMID 41514930, 2025). "Consistently, hyperleptinemia resulting from diet-induced obesity enhances inflammatory macrophage activity, whereas deletion of LepR in these cells reduces systemic inflammation." (PMID 41516046, 2025). "Mutations in LEP, LEPR, POMC, and MC4R disrupt this regulatory loop, resulting in hyperphagia, reduced satiety, and early-onset obesity." (PMID 40281302, 2025). "Mutations in this gene are one of the most common causes of monogenic obesity, and together with the genes encoding leptin and LEPR, MC4R explains 30% of extreme obesity in children." (PMID 41150735, 2025). "Of note, a recent study reported that the activation of Arc GABA non-LepR neurons triggered massive obesity and leptin resistance with intact leptin-pSTAT3 signaling, suggesting a complex neural interaction between GABAergic neurons and LepRb." (PMID 41016636, 2025). "db/db mice are leptin receptor dysfunction mice that exhibit severe obesity and hyperglycemia, making them common animal models for T2D." (PMID 40136546, 2025). "A study in Italy that screened 209 patients with obesity for mutations in the MC4R, LEP, and LEPR genes identified only one novel pathogenic frameshift variant in the MC4R gene, which disrupted gene signaling." (PMID 40149731, 2025). "When compared to the increasingly common proopiomelanocortin (POMC) and leptin receptor (LEPR) gene mutations, melanocortin-4 receptor (MC4R) gene polymorphisms are seen to be linked to BED and obesity." (PMID 40077044, 2025). "The active free form of circulating leptin in individuals with obesity accounts for 85% of total leptin, inducing long-form leptin receptor (LepRb) desensitization through chronic overstimulation." (PMID 40278960, 2025). "Several of the identified loci have been implicated in ASCVD risk factors such as circulating lipids (LPA-PLG, APOE, TRIB1, KANK2), diabetes (CDKN2B-AS1, IGF2BP1) and obesity (LEPR, IGF2BP1)." (PMID 40164586, 2025). "The current study investigates if there are sex differences in obesity-induced renal inflammation in SS leptin receptor mutant (SSLepR mutant) rats as a model of metabolic syndrome." (PMID 41463113, 2025). "Here, we investigated virus-host interactions under the effects of these comorbidities in diet-induced obesity (DIO) and leptin receptor-deficient (T2DM) mice following infection with SARS-CoV-2." (PMID 40125513, 2025). "In 2020, the FDA approved setmelanotide (Imcivree) for chronic weight management in patients with obesity due to POMC, PCSK1, or LEPR deficiency." (PMID 40636093, 2025). "Since obesity induced by chronic activation of non-LepR neurons is leptin resistant, we next explored the possibility that non-LepR neurons function directly downstream of LepR neurons." (PMID 40540394, 2025). "Increasing data indicates that SNPs and rare mutations in genes such as FTO, MC4R, LEPR, and POMC influence not only the risk of obesity but also significantly impact weight loss, WR, and metabolic outcomes following bariatric surgery." (PMID 41226372, 2025). "Implementing next-generation sequencing (NGS) to identify variants in Lep, LepR, MC4R, and POMC genes enables timely, genetically guided interventions for non-syndromic early-onset obesity in children and adolescents." (PMID 40278960, 2025). "Out of the thirty-three genes for which selected genetic variants were reported as significantly associated with obesity, only four genes (LEP, LEPR, POMC, and MC4R) are known to be linked with monogenic obesity." (PMID 39457458, 2024).
Obesity (continued). "Hyperleptinemia has been observed in mice with diet-induced obesity, providing protection through the activation of the STAT3 pathway and beyond, compared to those with mutant LepR obesity." (PMID 38397015, 2024). "It is specifically indicated for adult and pediatric patients aged 6 years and older with obesity caused by POMC, proprotein convertase subtilisin/kexin type 1 (PCSK1), or leptin receptor (LEPR) deficiency." (PMID 38540684, 2024). "This impairment can result from reduced expression of leptin receptors (LepR) or altered signaling pathways, ultimately contributing to the progression of obesity." (PMID 38397015, 2024). "The analysis of the LEPR gene, along with other obesity-related genes, underscores the complexity of genetic contributions to obesity and highlights the importance of considering genetic profiles in obesity research and intervention strategies." (PMID 39203789, 2024). "The other two are small molecules (glibenclamide to treat neonatal diabetes mellitus and setmelanotide to treat obesity associated with biallelic pro-opiomelanocortin (POMC), including PCSK1, deficiency obesity or leptin receptor (LEPR) deficiency obesity)." (PMID 38413985, 2024). "For example, mutations in the genes encoding melanocortin 4 receptor (MC4R), leptin receptor (LEPR), and pro-opiomelanocortin (POMC), result in monogenic obesity." (PMID 38806863, 2024). "The obesity and diabetes genes fat mass and obesity-associated (FTO), carnitine palmitoyl transferase 1A (CPT1A), leptin receptor (LEPR), and lamin A/C (LAMIN) genes were significantly down-regulated in the cardamom group." (PMID 38558676, 2024). "As expected in the leptin-resistance obesity model, the deficit in LEPR expression was counteracted by increased leptin expression." (PMID 38730110, 2024). "Mice with a pan-neuronal deletion of signal transducer and activator of transcription 3 (STAT3), the best-known transcriptional effector of leptin action, exhibit profound obesity which is similar to that seen in leptin receptor null mice." (PMID 38821928, 2024). "And db/db mice (leptin receptor mutant) are a common animal model that develops metabolic diseases such as obesity and insulin resistance in adulthood." (PMID 38568153, 2024). "Rare monogenic obesity primarily involves gene defects related to the leptin-melanocortin pathway, such as the LEP gene encoding leptin, the LEPR gene encoding leptin receptors, and SH2B1." (PMID 39232780, 2024). "The mechanism involves a decrease in caloric intake and an increase in the expenditure of energy, ultimately contributing to the management of obesity in individuals with specific genetic conditions such as POMC, PCSK1, or LEPR deficiencies." (PMID 38540684, 2024). "Our study, a placebo-controlled randomized trial, delves into the efficacy of specific dietary fiber supplements—glucomannan, inulin, and psyllium—in individuals with obesity-related genetic polymorphisms within genes such as FTO, LEP, LEPR, and MC4R." (PMID 38398881, 2024). "Different from ob/ob and db/db mice with the abolished leptin/LepR signaling, obese mice induced by a diet of 35% fat develop hyperleptinemia, irrespective of genotype, which are similar to most humans with obesity." (PMID 38704393, 2024). "In these studies, we assessed the response to leptin 2 weeks after virus injection, which was before the time that the BNC2 LepR knockout mice developed obesity." (PMID 39478220, 2024). "Patients with SRC1 mutations and severe obesity have been enrolled in phase 2 clinical trials of setmelanotide, an MC4R agonist, approved for obese patients with POMC or LEPR mutations." (PMID 38397265, 2024). "The drug is also indicated for obesity-related to proopiomelanocortin (POMC), proprotein convertase subtilisin/kexin type 1 (PCSK1), or leptin receptor (LEPR) deficiency." (PMID 39211725, 2024). "It involved 112 adults with obesity, each with at least one minor allele in the FTO, LEP, LEPR, or MC4R polymorphism." (PMID 38398881, 2024).